RN7SL569P (RNA, 7SL, cytoplasmic 569, pseudogene)
Gene: Miscellaneous RNA gene on chromosome 7 (148,890,226 to 148,890,513, forward strand). Ensembl gene ENSG00000239468.
Homologues: Orthologues: chimpanzee Metazoa_SRP (99% identical), macaque Metazoa_SRP (86% identical). Paralogues in human: RN7SL3 (74% identical), RN7SL1 (73% identical), RN7SL2 (73% identical), RN7SL333P (73% identical), RN7SL122P (72% identical), RN7SL220P (72% identical), RN7SL341P (72% identical), RN7SL587P (72% identical), RN7SL709P (72% identical), RN7SL83P (72% identical), RN7SL408P (72% identical), RN7SL493P (72% identical), and 702 more.